IL6 (interleukin 6)
Diseases named in the same sentence as IL6 in open-access papers (continued):
Sharing a sentence is not in itself a finding about the gene and the disease.
COVID-19 (continued). "A significant rise in C-reactive protein (CRP), aspartate aminotransferase (AST), procalcitonin, lactate dehydrogenase (LDH), IL-6 and ferritin was seen in the COVID-19 patients, indicative of the ongoing inflammatory response and tissue damage." (PMID 34344929, 2021). "Most patients with severe COVID-19 exhibit substantially elevated serum levels of pro-inflammatory cytokines such as IL-6 and IL-1β." (PMID 34646783, 2021). "In COVID-19 infected women, the production of inflammatory IL-6 (one of the main components of cytokine storm) is lower than in males and is often correlated with a better longevity." (PMID 33914806, 2021). "In patients with COVID-19, IL-6, TNF-α and IFN-γ have been confirmed to be critical pathogenic cytokines involved in the inflammatory storm." (PMID 34299225, 2021). "Neurologic complications during COVID-19 have previously been described as originating from a surge of inflammatory cytokines, such as IL6, which damages the central nervous system." (PMID 33557330, 2021). "In COVID-19, the immune response is characterized by high plasma levels of interleukins (IL-6, IL-2), interferons (IFN-y,) chemokines (CXCL10, CCL2, CCL3), growth factors (granulocyte colony stimulating factor) and tumor necrosis factor (TNFα)." (PMID 33557908, 2021). "Patients with COVID-19 showed an increase in TF expression as a possible consequence of lungs tissue damage and inflammation, leading to induction of IL-6." (PMID 34205975, 2021). "An Asian-common IL-6 haplotype defined by promoter SNP rs1800796 and intronic SNPs rs1524107 and rs2066992 correlated with COVID-19 severity." (PMID 34634929, 2021). "Most studies hold the view of blocking IL-6 and other signals and cytokines in the early period was beneficial for specific and adverse immune responses in COVID-19 patients." (PMID 34177566, 2021). "Elevated IL-6 in particular is associated with SARS-CoV-2 viral loads in serum and is strongly correlated with the severity of COVID-19 in humans." (PMID 34772941, 2021). "This is the reason for IL-6 being used as a biomarker for the inflammation levels in patients with cancer, infections, autoimmune diseases, or COVID-19." (PMID 34639073, 2021). "Immune checkpoint inhibitors (ICI) and CAR-T cell mediated cancer immunotherapy usually lead to hyper activation of IL-6, IFN- γ and other cytokines, causing severe illness and death, a condition similar to that observed in severe COVID-19 patients." (PMID 34356617, 2021). "Even though IL-6 and IL-10 were noted as predictors for COVID-19 deterioration, all of our patients were followed up in the hospital but not in ICU." (PMID 34384355, 2021). "Another hallmark of severe COVID-19 is the cytokine storm associated with elevated levels of cytokines (IL1β, IL1Rα, IL2, IL6, IL7, IL10, G-CSF, TNFα), chemokines (IP10, MCP1, MIP1α) and endogenous neutrophil calprotectin." (PMID 34867943, 2021). "In a meta-analysis, serum levels of interleukin-2 (IL-2), IL-2R, IL-4, IL-6, IL-8, IL-10, tumor necrosis factor-alpha (TNF-α), and interferon-gamma (INF-γ) were found to be associated with severe COVID-19 cases." (PMID 34855834, 2021). "Upregulation of IL-6 has been reported in COVID-19 patients and is a contributing factor to cytokine storm and the development of ARDS." (PMID 34714894, 2021). "IL-6 was another immunological factor that was elevated in COVID-19 patients, with severe COVID-19 having more elevation than in non-severe COVID-19 patients." (PMID 34829418, 2021). "Markers of systemic inflammation implicating CRP and IL-6 were elevated in patients with poor outcomes, and the origin of the dysregulated release of cytokines in COVID-19 has been ascribed to various factors." (PMID 34360751, 2021). "IL-6 is elevated in the serum of COVID-19 patients, especially in those presenting with severe disease, as part of a cytokine storms." (PMID 33794925, 2021).
COVID-19 (continued). "COVID-19 therapies included hydroxychloroquine (64% of patients), remdesivir (4%), corticosteroids (20%), and IL-6 inhibitors (5%)." (PMID 34797838, 2021). "High levels of IL-6 or its read-out protein CRP in serum should alert the medical staff that the course of COVID-19 can take a turn for the worse." (PMID 34149697, 2021). "The majority (20/25, 80%) of patients with cardiovascular and cerebrovascular diseases and COVID-19 showed elevated IL-6 levels." (PMID 34123873, 2021). "Specifically, IL-6 levels ≥24.3 pg/mL and D-dimer > 0.28 μg/L were closely correlated with the occurrence of severe COVID-19, and with their combined detection provided the highest specificity and sensitivity for early prediction of disease severity and death." (PMID 33550983, 2021). "Higher C-reactive protein, neutrophil-to-lymphocyte ratio, lactate dehydrogenase and interleukin (IL)-6 are normally found in severe COVID-19 and predict fatal outcome." (PMID 34572439, 2021). "Previous studies have found an association between an increase in levels of IL-2, IL-6, IL-7, IL-10 and TNF-α and the severity or mortality of COVID-19." (PMID 34490065, 2021). "On the other hand, FIB-4 in acute COVID-19 can reflect systemic inflammation because of positive correlations with IL-6 and IP-10." (PMID 34635073, 2021). "Especially in the case of COVID-19, it is worth mentioning that IL-6 is an inducer of differentiation of Th17, while IL-17 induces the secretion of IL-6." (PMID 34064728, 2021). "Tocilizumab (TCZ) an IL-6 receptor antagonist has also been used as a potential treatment in patients with COVID-19 due to its ability to block the IL-6 mediated inflammatory response." (PMID 33614514, 2021). "Our results show that plasma gp96 and IL-6 levels were weakly correlated in COVID-19 patients, while gp96 was found to be a strong inducer of IL-6 in vitro." (PMID 34817280, 2021). "The critical role of IL-6 in the pathophysiology of severe COVID-19 justified its treatment with tocilizumab—a monoclonal antibody against the IL-6 receptor." (PMID 35011848, 2021). "Cytokine profiles in COVID-19 patients have revealed increased levels of interleukin-1β (IL-1β), IL-2, IL-6 and tumor necrosis factor-alpha (TNFα)." (PMID 33927728, 2021). "COVID-19 is characterized by a state of pulmonary hyper-inflammation and cytokine storm, the suggested culprit of which is interleukin-6 (IL-6) as well as other cytokines." (PMID 34109302, 2021). "A retrospective study of 522 patients with COVID-19 found that a clinical severity-dependent reduction in the number of T cells is inversely correlated with the serum level of interleukin 6 (IL-6)." (PMID 34646783, 2021). "In another study, maximal IL-6 (>80 pg/mL) and CRP (>97 mg/L) levels before intubation showed the strongest association with the need for mechanical ventilation in a cohort of COVID-19 hospitalized patients." (PMID 33815405, 2021). "Considering the major role of IL-6 in the pathophysiology of COVID-19, sarilumab as another mAB against IL-6 was suggested to alleviate respiratory symptoms." (PMID 34812049, 2021). "Of the arsenal of therapeutics proposed as anti-COVID-19 candidates, the anti-IL-6 mAbs seemed to be useful in severe patients." (PMID 34073559, 2021). "We analyzed a range of indicators associated with severe COVID-19 and developed a novel predictive model that included ALT, IL-6, expectoration, fatigue, LYMR, AST, and CREA." (PMID 34113636, 2021). "In line with our results, a recent study reported IL-6 serum levels to be 27-times lower in COVID-19 patients than in septic shock patients, therefore questioning the existence of a cytokine storm in COVID-19." (PMID 34193220, 2021). "The AGE-RAGE signaling pathway based on IL6 was significantly involved in the mechanisms of LHQW treatment of COVID-19 in KEGG pathway analysis." (PMID 34731090, 2021).
COVID-19 (continued). "We also assessed plasma levels of three major proinflammatory cytokines, IL-1β, IL-6 and TNFα, and IL-10, an anti-inflammatory cytokine, in COVID-19-naive older adults." (PMID 34868051, 2021). "Numerous studies have discovered greater IL-6 concentrations in post-mortem specimens from COVID-19 cases." (PMID 34777870, 2021). "A multitude of interventional trials are based on the paradigm of typical hypercytokinemia (such as in MAS) in critically ill COVID-19 patients, as a result thereby investigating immunomodulatory therapies such as anti-IL-6 or IFN-γ/IL-1 blockade." (PMID 34226537, 2021). "We found 35 novel drugs that inhibit targets (ALPL, CXCL8, and IL6) already in clinical trials for COVID-19." (PMID 34582497, 2021). "The effects of off-label Tocilizumab treatment of COVID-19 patients suggested that IL-6 plays a critical role in impairing antigen presentation and antiviral cytotoxicity in severe patients." (PMID 33912590, 2021). "Signature cytokines in severe COVID-19 include enhanced expression of IL-6, IL-1β, IL-1α, IL-2, IL-7, IL-10, TNFα, MIP1α, MCP1, G-CSF, IFNγ." (PMID 34198973, 2021). "Several studies have attempted to seek the predictors of disease progression of COVID-19, such as Neutrophil-to-lymphocyte ratio, thrombocytopenia, DD, IL-6 and so on." (PMID 34088324, 2021). "In COVID-19 patients, the pro-inflammatory cytokines like IL-1, IL-2, IL-6, IL-7, IL-10, IP-10, and TNFα as well as chemokines like IL-8 are found in higher concentrations." (PMID 33981235, 2021). "Adipose tissue can act as a reservoir for the production and secretion of IL-6 and hence amplify the cytokine storm and contribute to higher mortality in COVID-19." (PMID 33824998, 2021). "COVID-19 can spur glial cell activation and heightened inflammation in the CNS through the escalation of IL-6, IL-12, and IL-15, as well as tumor necrosis factor-alpha (TNF-α)." (PMID 32789802, 2021). "The expression of IL-6 was significantly increased in leprosy/COVID-19 during our multivariate analysis." (PMID 33819170, 2021). "An excessive amount of pro-inflammatory cytokines, including tumor necrosis factor-alpha (TNF-α), interleukin (IL)-1β, and IL-6, has been reported in most COVID-19 patients." (PMID 33708378, 2021). "Accordingly, some ongoing RCTs are studying glucocorticoids and blockage of IL-1, IL-6, and IFNγ in COVID-19." (PMID 33495742, 2021). "The possibility that IL-6 worsens COVID-19 outcomes has led to anti-IL-6 therapy trials with tocilizumab and sarilumab, but the results have been mixed." (PMID 34441038, 2021). "Autopsy findings indicated massive lymphocyte death in the spleen and enlarged intrathoracic lymph nodes of patients who died from COVID-19; a possible role of IL-6 and the Fas–FasL interactions was proposed." (PMID 34603758, 2021). "In stroke patients with COVID-19, the cytokines IL-1β, IL-6, and TNF-α are representative as well as in the CSF and blood serum." (PMID 34577633, 2021). "Another mechanism that can suppress NK cell antiviral activity is the elevated IL-6 and IL-10 levels in COVID-19 through the down-modulation of the activating receptor NKG2D." (PMID 35062250, 2021). "The anti-inflammatory and antiviral activity of baricitinib was demonstrated by its ability to reduce viral infectivity in human primary liver spheroids and in COVID-19 patients exhibiting a rapid decline in viral load, inflammatory markers and IL-6 levels." (PMID 34356617, 2021). "With high Interleukin -6 (IL-6) levels reported in COVID-19 related deaths in China, IL-6 is considered to be the key player in COVID-19 cytokine storm." (PMID 33673818, 2021). "In severe COVID-19 patients, serum levels of proinflammatory cytokines including IL-2, IL6, IL-7, IL-10, G-CSF, IP-10, MCP-1, MIP-1α and TNFα are highly elevated." (PMID 33643932, 2021). "Proinflammatory cytokines in the blood were found to be upregulated in COVID-19 patients, including interleukin- (IL-) 1, IL-6, tumor necrosis factor (TNF), and interferon γ." (PMID 34580601, 2021).
COVID-19 (continued). "The present study shows that CRP, LDH, ferritin and IL-6 are related not only with COVID-19 severity but also with mortality." (PMID 34439469, 2021). "It has been shown that ferritin and IL-6 are useful in monitoring disease progression and severity of cytokine storm in COVID-19 patients; recovering patients were observed to have down-trending ferritin and IL-6 levels." (PMID 34698139, 2021). "In combination with TGF-β1, a high level of IL-6 in the sera of patients with severe COVID-19, induces the differentiation of Th17 and inhibits iTreg (TGF-β1-induced Treg) generation." (PMID 35126355, 2021). "Regarding C. albicans responses, there was a lower release of IL-6, TNF, IL-1α, and IL-1β, and it was concluded that COVID-19 cases are more susceptible to Candida spp." (PMID 34575758, 2021). "The cytokines involved in the pathogenesis of lung inflammation in COVID-19 include IL-1, IL-6, IL-8, and TNF-α." (PMID 34065210, 2021). "Individuals with COVID-19 have been reported to have high levels of major inflammatory cytokines such as IL-6, IL-1β, and TNF-α in the circulation, which was associated with the magnitude of disease severity." (PMID 33959020, 2021). "According to Otsuka and Seino, in patients (n = 1302) with severe COVID-19, IL-6 was three times higher than in patients with a mild or moderate course (p < 0.001)." (PMID 34205217, 2021). "In patients with COVID-19, the severity of the disease is directly proportional to the concentration of IL-2R and IL-6, distinguishing the disease status by critically ill, severely ill, and normal patients." (PMID 33946736, 2021). "Several immunomodulatory agents targeting IL-6 and IL-1 blockade were proposed as potential therapeutic options for severe COVID-19 to inhibit the proinflammatory effect and its consequences on pulmonary and other organ function." (PMID 34830648, 2021). "TNF induced the production of IL-6 and other cytokines, involved in the process of cytokine storm in COVID-19." (PMID 34313585, 2021). "Recent studies have shown increased cytokine levels, specifically interleukin 6 (IL-6), in critically ill patients with COVID-19." (PMID 34724920, 2021). "In a retrospective multiple-center study that enrolled 267 laboratory-confirmed coronavirus disease 2019 (COVID-19) cases, most patients had high plasma concentrations of IL-6 and IL-17A." (PMID 34602860, 2021). "Seventy-one studies were included involving 8647 COVID-19 patients, White blood cell (WBC), neutrophil (NEUT), IL-6, and IL-10 counts increased significantly with worsening of the COVID-19, while lymphocyte (LYM) counts decreased." (PMID 33557779, 2021). "Various studies on the clinical characteristics of COVID-19 patients unveiled an elevation in IL-6 concentration." (PMID 34205852, 2021). "The resulting cohort dynamics were within ranges for IFN and IL-6 measurements in asymptomatic to severe COVID-19 patients in the literature." (PMID 34260666, 2021). "Patients with severe COVID-19 show extreme cytokine storms involving the overexpression of IL-2 and IL-6." (PMID 33445583, 2021). "Interleukin6 (IL-6) is a key driver of hyperinflammation in COVID-19, and its level strongly correlates with disease progression." (PMID 34634929, 2021). "For example, the IL-6 monoclonal antibody, Tocilizumab, tested in phase II trials, has been shown to reduce COVID-19 lethality rate." (PMID 34361021, 2021). "Recently, tocilizumab, a monoclonal antibody drug targeting IL-6, has been shown to have therapeutic potential for the treatment of COVID-19,68 which also highlights the vital role of anti-inflammatory response in current therapeutics against SARS-CoV-2." (PMID 33895786, 2021). "CAM can be a side effect or even a superinfection due to corticosteroids, anti-IL-6 therapy, and antibiotics to manage severely ill COVID-19 patients." (PMID 34682258, 2021).
COVID-19 (continued). "In this scenario, COVID-19 pandemic has placed under the spotlight the correlation among IL-6, cytokine release syndrome, hyperinflammation state and COVID-19 fatality rate." (PMID 34836187, 2021). "We showed IL-6 to be related to disease severity in mild to severe cases of COVID-19 in the MGH cohort." (PMID 35095877, 2021). "In severe COVID-19, macrophages in the lungs activate and produce large amounts of proinflammatory cytokines, mainly IL6." (PMID 34075090, 2021). "Another study revealed that peripheral blood immune cells from severe COVID-19 patients have diminished type-I IFN response but enhanced pro-inflammatory IL-6 and TNF-α responses." (PMID 34835108, 2021). "IL-6 production shows a key role in virus-mediated inflammation and, in particular, on COVID-19 complications." (PMID 34829949, 2021). "The interaction test between IL-6 and MAFLD status on risk of severe COVID-19 was found to be statistically significant (p-value for interaction = 0.008)." (PMID 33763027, 2021). "MAS is involved in coronavirus disease-19 (COVID-19), and the blockade of pro-inflammatory cytokines by an anti-IL-6 or IL-6R antibody, such as Tocilizumab, has already been employed for the treatment of MAS and COVID-19 in patients." (PMID 35008658, 2021). "Excessive production and release of cytokines such as tumor necrosis factor (TNF), interleukin (IL)-1, and IL-6 are characteristic of COVID-19." (PMID 34094634, 2021). "Recent findings reported increases in serum inflammatory cytokine (e.g., IL-2R, IL-6, IL-8, IL-10) in severe COVID-19 patients." (PMID 33390771, 2021). "In line with this evidence, we found that the level of several soluble proinflammatory markers were increased (e.g., CRP, ferritin, IP-10, and IL-6) in the >65 years compared to <65 years COVID-19 patients." (PMID 34682920, 2021). "Recent reports especially highlight the role of interleukin-6 (IL-6) in the pathogenesis of COVID-19, but also the role of IL-6 inhibitors in COVID-19 therapy." (PMID 33841339, 2021). "In one case report of compassionate use in severe COVID-19, administration of Wharton’s jelly-derived MSCs reduced plasma levels of IL-6, TNF-α, and C-reactive protein and improved lung function." (PMID 33584343, 2021). "The treatment of COVID-19 patients consists of antipyretics, oxygen therapy, steroids, low molecular weight heparin, anti-viral therapy (remdesivir), IL-6 antagonist (Tocilizumab) and broad-spectrum antibiotics." (PMID 34589359, 2021). "A decline in nitric oxide (NO) bioavailability is another key aspect of a dysfunctional endothelium in COVID-19, potentially depending on the high levels of circulating interleukin 6 (IL6) and other inflammatory markers." (PMID 34071308, 2021). "Previous data suggested that the most important sources of IL-6 in COVID-19 patients were circulating monocytes." (PMID 33692788, 2021). "The pro-inflammatory cytokine IL-6 has been suggested to be involved in the aggravation of patients with COVID-19." (PMID 34684771, 2021). "Severe COVID-19 has been reported to be characterized by hyperinflammation with excessive cytokine production, which results in lymphopenia and IL-6-mediated inhibition of HLA-DR expression." (PMID 34356969, 2021). "Tocilizumab is a recombinant monoclonal antibody against IL-6 that is now being tested in COVID-19 patients for the treatment of ARDS." (PMID 34835248, 2021). "The enhanced IL-6 level in serum was demonstrated in several studies of COVID-19 and was correlated with patient mortality." (PMID 33670394, 2021). "High IL-6 levels in COVID-19 patients are considered an immunological sign of ongoing cytokine storms." (PMID 34123873, 2021). "The highest median inflammatory marker hs-CRP, IL-6, and ferritin levels and the highest median IgG, IgM, and neutralizing antibody levels were noted in hospitalized COVID-19 patients." (PMID 34111164, 2021).